MTOR (mechanistic target of rapamycin kinase)
Diseases named in the same sentence as MTOR in open-access papers (continued):
Sharing a sentence is not in itself a finding about the gene and the disease.
tumor (continued). "In addition, mTOR and CDCA5 has been extensively reported to regulate immune cell function and activity as well as tumor immunity." (PMID 38658931, 2024). "In addition to apoptosis, autophagy is also activated upon radiation and TMZ in GBM cells and act to halt tumor growth via the degradation of oncogenic proteins, stimulation of AMPK and inhibition of Akt/mTOR signaling." (PMID 38890642, 2024). "Additionally, the combined treatment of ellagic acid and sorafenib displayed enhanced anti-tumor effects, highlighting the importance of targeting MAPK and Akt/mTOR signaling pathways for improved therapeutic results." (PMID 39185304, 2024). "As a dual inhibitor targeting both PI3K and mTOR, VS-5584 (SB2343) efficiently decreased the number of tumor spheres and induced apoptosis of CSCs when co-treated with paclitaxel (PTX), which regulates the cell cycle to stay at G2, inhibiting the cell division." (PMID 39349424, 2024). "Previously, we identified that tumor-suppressive miR-99b-5p is frequently downregulated in aggressive African American (AA) PCa and European American (EA) CRPC, leading to upregulation of mTOR, androgen receptor (AR), and HIF-1α signaling." (PMID 38792011, 2024). "PI3K and AKT/mTOR pathways upregulate ER activation and improve glucose uptake, which are not pro-tumorigenic processes, but rather increase anti-tumor activity." (PMID 38672654, 2024). "When combined with anti‐PD‐1, PI3K/mTOR inhibition led to partial or complete tumour responses, whereas no response to single‐agent anti‐PD‐1 was observed." (PMID 38711203, 2024). "Additionally, we observed enrichment in genes that take part in the signaling pathway of phosphatase and tensin homologue (PTEN), known to suppress tumor growth and metastasis via inhibition of PI3K/Akt/mTOR." (PMID 38612755, 2024). "In addition, W. coagulans MZY531 regulates the Bax/Bcl-2/caspase-3 and JAK2/STAT3 apoptosis pathways and PI3K/AKT/mTOR pathways, as well as TGF-β/SMAD4 autophagy pathways, thereby attenuating tumor growth." (PMID 39459634, 2024). "To explore whether the AKT-mTOR pathway is involved in pitavastatin-reduced or CD36-induced cell proliferation, we determined the activation of AKT and mTOR in cells and tumor tissues." (PMID 38319449, 2024). "The combined use of NCTD and crizotinib can significantly inhibit the growth of tumors in tumor-bearing mice, and the effect is better than that of a single drug, which may be related to NCTD inhibiting the mTOR pathway." (PMID 38803433, 2024). "The authors reported that the pharmacological inhibition of mTOR induced the emergence of chemoresistant noncycling tumor cells that exhibited a senescence phenotype." (PMID 38418814, 2024). "We demonstrate the key role of KIRREL in tumour progression and speculate that it might promote tumour cell proliferation and angiogenesis by activating the PI3K/AKT/mTOR pathway, revealing KIRREL as a potential target for GC therapy." (PMID 37909722, 2024). "It was reported that FAN at concentrations from 1 to 3 mg/kg could significantly attenuate the tumor volume and weight in mice by suppressing the PI3K/AKT/mTOR pathway, suggesting it is likely feasible to use FAN for in vivo application." (PMID 39000284, 2024). "Also, apigenin, which elicits oxidative and anti-tumor effects, induces autophagy, and inhibits cell proliferation by inhibiting the PI3K/Akt/mTOR pathway." (PMID 39519229, 2024). "Similarly, in vivo studies investigating the ATP-competitive mTOR inhibitor, AZD8055, demonstrate the reduced phosphorylation of both S6 and Akt with the subsequent reduction of tumor growth." (PMID 38474373, 2024). "The exact function of Interleukin-7 (IL-7) in controlling tumor cell autophagy, lymphangiogenesis, growth, and cell death is not completely clear; studies are centered on mTOR and Beclin-1." (PMID 39650649, 2024).
tumor (continued). "Furthermore, our findings revealed that a heightened cell adhesion effect correlated with tumor resistance to DNA-damaging drugs, protein kinase inhibitors, and drugs targeting the PI3K/Akt/mTOR signaling pathway." (PMID 38560563, 2024). "Furthermore, GSEA analysis showed reductions in genes related to anti-tumor immune responses including the IL-2/STAT5 pathway, the interferon-gamma response and the PI3K/AKT/mTOR signaling." (PMID 38659818, 2024). "Furthermore, it reduced TGF-β-induced morphological changes and suppressed tumor cell invasion and migration by decreasing the phosphorylation of the PI3K/Akt/mTOR signaling pathways." (PMID 38794168, 2024). "Additionally, studies show that tipifarnib suppresses tumour aggressiveness in several malignancies and low-dose tipifarnib had antitumour effects only on HIF-1α-positive cells through the mTOR singling pathway, both in vitro and in vivo in GC model." (PMID 38817874, 2024). "Tumor-derived EVs, containing certain miRNAs, contribute to the enhanced TGF-beta expression in CAFs through the phosphoinositide 3-kinase (PI3K)/protein kinase B (AKT)/mammalian target of rapamycin (mTOR) signaling pathway." (PMID 38672654, 2024). "Expression of activated forms of mTOR and STAT3 significantly reduced tumor cell killing." (PMID 38758815, 2024). "The previous findings have proved that mTOR is essential for CDCA5 function in ccRCC, we thus examine whether the pro-tumor function of CDCA5/EEF1A1 was via mTOR pathway." (PMID 38658931, 2024). "Tumor sphere formation experiment results showed that the tumor sphere formation rate of MDA-MB-436 cells was increased after OPN was overexpressed, which subsequently declined to some extent following the inactivation of PI3K/AKT/mTOR signaling pathway." (PMID 38526702, 2024). "This article reviews the dysregulation of the EGFR, PI3K/AKT/mTOR, Hippo, pyroptosis, and PD-1/PD-L1 signaling pathways in HBC and CMT, as well as the corresponding drugs used to inhibit tumor growth, with the aim of providing theoretical support for the development of more efficient drugs." (PMID 39796003, 2024). "Furthermore, the brain microenvironment can be significantly enhanced by tumor cells through the stimulation of growth factor receptors and activation of the AKT/PI3K/mTOR, MAPK, and NF-κB signaling pathways." (PMID 38243240, 2024). "Moreover, the expression of miR-34a and miR-34b was significantly lower in tumor tissues, and their levels were inversely correlated with the expression of the PI3K/AKT/mTOR pathway proteins." (PMID 39512697, 2024). "Our current information suggests that an mTOR-dependent enhancement of ATP production and HIF-1α levels may contribute to this LMP2A-dependent enhancement in MYC-driven tumor development and potentially the need to bypass additional oncogenic mutations." (PMID 38612754, 2024). "Research has indicated that circ_0003945 could alter the biological behaviors of tumor cells by modulating signaling pathways such as MAPK, Wnt/β-catenin, PI3K/AKT/mTOR, Rac-FAK1, and others." (PMID 38711855, 2024). "Further analysis of the upregulated genes for enrichment in signaling pathways using GSEA revealed a significant enrichment of the PI3K/AKT/mTOR pathway in the tumor tissue of non-responders." (PMID 38529286, 2024). "Tumor tissues with TLS are characterized by inflammatory signatures and high infiltration of antitumor immune cells, while those without TLS exhibit uncontrolled cell cycle progression and activated mTOR signaling by bulk and single‐cell RNA‐seq analyses." (PMID 38498682, 2024).
tumor (continued). "Moreover, in addition to tumor suppression, the combination therapy of TP-0903 and WIN55212-2 induced the infiltration of cytotoxic CD8+ T cells and significantly reduced mTOR and STAT3 activation in tumor tissues of C57BL/6J mice bearing MC-38 cells." (PMID 39598377, 2024). "ERBB3 influences PI3K/AKT/mTOR pathway activation and epithelial−mesenchymal transition (EMT) in CC, contributing to immune evasion and tumor development, and may interact with immune checkpoints to facilitate tumor escape." (PMID 38835778, 2024). "After carefully reviewing the current knowledge, the use of CRMs might be recommended when a particular pathway, such as PI3K/AKT/mTOR or IGF1/IGFBP, is upregulated in the tumor and can be modulated by the intervention." (PMID 39195514, 2024). "We have previously shown that the PI3K/AKT/mTOR and RAS/RAF/ERK pathways converge on key cellular processes, including Cyclin D-Cdk4/6 activation and cap-dependent translation and that both pathways must be inhibited to affect tumor growth or survival." (PMID 39025835, 2024). "We performed immunohistochemical analyses on tumor tissues from four treated groups to assess whether YAP inhibitor combined with trastuzumab therapy, which acts through the AKT/mTOR and ERK/mTOR pathways can be replicated in vivo." (PMID 38782859, 2024). "mTOR suppression induces eIF3D-mediated selective mRNA translation in non-proliferative tumor cells." (PMID 38418814, 2024). "Additionally, inhibiting AKT has also been found to enhance the expansion of potent tumor-specific T cells with memory properties, indicating the potential of controlling AKT/mTOR signaling as a strategy for promoting memory T-cell development." (PMID 38891056, 2024). "Moreover, multiple signaling pathways contribute to the anti-tumor effects of Huangqin, such as NF-κB, Wnt/β-catenin, SATB1, Bcl-2 family proteins, Caspase, PI3K/Akt, mTOR, ERK, p38-MAPK, TGF-β/Smad, and Hippo/YAP pathways." (PMID 38993643, 2024). "The dependence of tumor cells on multiple oncogenic pathways and poor tolerability could contribute to the failure of monotherapy with pan-PI3K and mTOR inhibitors in solid cancers, including CRC." (PMID 38542151, 2024). "In RCC, activation of the mTOR pathway, downstream of the PI3-K/AKT pathway, leads to carcinogenesis by directly promoting the growth of tumor cells or by increasing the expression of hypoxia-inducible factor (HIF)-1α and HIF-2α, which are also involved in renal tumorigenesis." (PMID 39100549, 2024). "Additionally, GSVA analysis revealed an activation of tumor progression-related pathways, including DNA repair, PI3K/AKT/MTOR signaling, and Wnt/β-catenin signaling, in the high-ZMIZ2 group." (PMID 38254216, 2024). "Notably, tumour suppressor genes like PTEN, which inhibit mTOR signalling, act as facilitators of autophagic processes." (PMID 38893278, 2024). "Transcriptional regulation by key transcription factors like SREBP1 and PRP19, as well as activation of signaling pathways such as PI3K/Akt/mTOR and MAPK pathways, may also contribute to FA upregulation and enhance tumor cell proliferation." (PMID 38699187, 2024). "Our results indicated that the PI3K/AKT/mTOR signaling pathway inhibitor could reverse DCLK1-mediated tumor progression, suggesting that CCA populations with high DCLK1 expression may benefit from therapies targeting the PI3K/AKT/mTOR pathway." (PMID 38980538, 2024). "The PI3K/AKT/mTOR pathway in CD133-positive cells contributes to their enhanced capacity for survival and resistance to environmental stress, such as nutrient deprivation or hypoxia, which is common in tumor microenvironments." (PMID 39456981, 2024).
tumor (continued). "Additionally, GA induces oxidative stress, activates the mitochondrial apoptotic pathway, inhibits angiogenesis, and modulates key signaling pathways such as PI3K/Akt/mTOR (mammalian target of rapamycin) and MAPK/ERK suppressing tumor growth." (PMID 39199245, 2024). "Findings from our study were consistent with those in previous studies and further revealed that miR-30a-3p, acting as a tumor suppressor, was directly sponged and downregulated by circ_PPAPDC1A, with upregulation of IGF1R and activation of IGF1R/PI3K/ AKT/mTOR signaling." (PMID 38715012, 2024). "In conclusion, we found that OPN could promote tumor sphere formation and angiogenesis in TNBC by activating the PI3K/AKT/mTOR pathway to regulate GPX4-mediated anti-lipid peroxidation levels." (PMID 38526702, 2024). "Furthermore, in a dose-dependent manner, Salmonella treatment led to a decrease in the phosphorylation of AKT, mTOR, and p70S6K, thereby indicating downregulation of the AKT/mTOR/p70S6K/β3-adrenoceptor pathway by Salmonella treatment in tumor cells." (PMID 38356700, 2024). "In addition, pathways related to tumor proliferation (WNT/Beta-Catenin, PI3K/AKT/mTOR, MTORC1, MYC targets V1) and pathway related to DNA mismatch repair (DNA repair) also showed significant negative correlations with miR-24-1-5p expression." (PMID 38840234, 2024). "In addition, SIRT3 promotes tumour cell autophagy and drug resistance through theregulation of PI3K/mTOR pathway and downregulation of P26." (PMID 37996927, 2023). "The carcinogenic roles of ROS include genetic alterations, cell proliferation through the PI3K/AKT/mTOR and MAPK/ERK pathways, and promotion of the epithelial–mesenchymal transition, whereas their tumor-suppressive roles include apoptosis, necroptosis, and ferroptosis." (PMID 37262048, 2023). "During the process of tumour progression, DJ-1 activates the MAPK and AKT/mTOR signalling pathway via suppression of the PTEN gene, thereby promoting proliferation and survival by inhibiting apoptosis followed by invasion and metastasis of tumour cells." (PMID 37815438, 2023). "PI3K/Akt/mTOR and Raf/MEK/ERK are involved in ATC dedifferentiation and tumor growth." (PMID 37853445, 2023). "Additionally, to inspect the activation of tumor‐relevant signaling pathways at the level of protein, we included signaling hallmarks from TGF‐β/SMAD, NF‐κB, JAK–STAT, PI3K/AKT/mTOR, and Wnt signaling pathways." (PMID 36550781, 2023). "Combination of radiotherapeutics and mTOR inhibitors preclinically tested for [177Lu]Lu-PP-F11N in mice, has resulted in improvement of tumor uptake, presumably via the CCK2R-upregulation in tumor cells, offering hopes for a successful translation in the clinic." (PMID 37242457, 2023). "PTEN is a tumor suppressor and a critical regulator of AKT/MTOR pathway." (PMID 38003292, 2023). "In addition, the phosphatase and tensin homolog deleted on chromosome 10 (PTEN), a tumor suppressor, suppresses glycolysis, the pentose phosphate pathway, lipid synthesis, and pyrimidine synthesis by blocking AKT and mTOR signaling." (PMID 37860928, 2023). "In addition, researchers have found that abnormal activation of mTOR induces the production of PKM2 by upregulating a protein that plays a key role in tumorigenesis, thereby promoting aerobic glycolysis in tumor cells." (PMID 36994237, 2023). "c-MYC directly promotes CaP development through the upregulated expression of various pro-tumorigenic factors, including ribosome biogenesis, which supports tumor growth and PI3K/AKT/mTOR pathway dysregulation, consequently promoting the survival and growth of CaP cells." (PMID 37895357, 2023). "Bioinformatics analysis revealed gut microbiota may influence ICC development through regulating pathways like AMPK, mTOR, EGFR and tumor immune microenvironment." (PMID 38033576, 2023).
tumor (continued). "Interestingly, PI3KCA mutations, such as H1047R, demonstrate an abnormal sensitivity to mTOR/PI3K inhibitor BEZ-235 and a subsequent decrease in cell growth in HPV-positive HNC tumor graft models." (PMID 37237486, 2023). "We speculated that the mTOR signaling may promote the translation of ALKBH5 mRNA through certain protein kinases and increase the level of ALKBH5 protein, then affecting tumor metabolism." (PMID 37325047, 2023). "Taken together, our results demonstrate that pharmacological co-targeting of EGFR and MTOR using clinically available drugs represents an effective treatment paradigm for EGFR-driven GBMs, acting both by inhibiting tumor cell growth and modulating the immune tumor microenvironment." (PMID 36831214, 2023). "Activation of the PI3K/AKT/mTOR pathway results in phosphorylation of FOXO1 and prevents it from entering the nucleus, providing a mechanistic explanation for the enhanced anti-tumor effect of HDAC inhibitor and PI3K/mTOR inhibitor combination therapy." (PMID 37568705, 2023). "Taken together, our results demonstrate that Uro A treatment is a well-tolerated therapy that effectively reduces primary tumor growth, inhibits PI3K/AKT/mTOR signaling, suppresses intratumoral fibrosis and curtails inflammatory cytokine production in an aggressive mouse model of PDAC." (PMID 37448553, 2023). "The results revealed that the triple-drug combination markedly inhibited the protein expression of VEGF, VEGFR, PI3K, p-AKT, PDK, p-mTOR, Nrf2 and HIF-1α when compared to that of tumor-control (p < 0.001); while it significantly enhanced the expression of PTEN." (PMID 37025487, 2023). "The mTOR gene mRNA level was not changed (1.00-fold) in the Tumor+50 mg/kg melatonin group and the mTOR gene mRNA level was decreased in the Tumor+100 mg/kg melatonin group compared to the Control (Tumor) group (0.5-fold, p < 0.001)." (PMID 38188676, 2023). "Additionally, PI3K, AKT, and mammalian target of rapamycin (mTOR) inhibitors may serve as potential therapeutic options for patients with PIK3CA and PTEN mutations, whereas an mTOR inhibitor can be used as a therapeutic approach for targeting STK11- and FBXW7-deficient tumours." (PMID 38024139, 2023). "Furthermore, andrographolide acts on other cellular pathways regulation, including mTOR, Wnt/β-catenin, TRAIL-mediated apoptosis, as well as VEGF-mediated intracellular signaling, and adversely affects tumor development." (PMID 36986550, 2023). "Moreover, targeted inhibition of platelet-derived growth factor receptor (PDGFR) and phosphoinositide 3-kinase (PI3K)/mammalian target of rapamycin (mTOR) by imatinib mesylate and PKI-587 showed in vivo tumour suppression effects." (PMID 36522480, 2023). "Additionally, 149 was shown to cause cell cycle arrest at G2/M phase in T11 and SUM159PT cells, as well as inhibit the phosphorylation of the Akt/mTOR, MAPK and NF-κB pathways, which are responsible for tumour relapse and metastasis." (PMID 36771114, 2023). "The PI3K/AKT/mTOR signal transduction pathway and the Ras/MAPK pathway are hyperactivated in several cancer types, including glioblastoma, and play a key role in tumorigenesis by activating the tumor promoters and inhibiting the tumor suppressors." (PMID 36674870, 2023). "Additionally, propolis has been found to inhibit tumor cell proliferation through various signal pathways, including MAPK, PI3K/AKT/mTOR, JAK-STAT, TLR4-NF-κB, VEGF, and TGFβ." (PMID 37892405, 2023). "In leukemia cells, non-thermal plasma-treated solutions induces tumor cell death through RNF126-mediated mTOR ubiquitination degradation." (PMID 37190313, 2023). "According to previous studies, MAPK4 promotes tumor progression by activating the AKT/mTOR pathway in a noncanonical manner." (PMID 36999945, 2023).